GKN3P (gastrokine 3, pseudogene)
Description:
May inhibit gastric epithelial cell proliferation.
Gene: Unitary pseudogene on chromosome 2 (68,921,248 to 68,926,834, forward strand). Ensembl gene ENSG00000283586.
Subcellular location: Secreted
Diseases named in the same sentence as GKN3P in open-access papers:
GKN3P is named in the same sentence as 2 diseases in open-access papers, as found by Europe PMC text mining. Sharing a sentence is not in itself a finding about the gene and the disease.
GKN3P shares sentences with these, for which no sentence is quoted: cancer (1 paper); cognitive disease (1).